FH (fumarate hydratase)
Diseases named in the same sentence as FH in open-access papers (continued):
Sharing a sentence is not in itself a finding about the gene and the disease.
lung adenocarcinoma (2 papers, 2019 to 2021). A carcinoma that arises from the lung and is characterized by the presence of malignant glandular epithelial cells. "Survival analysis suggested high expression of FH was associated with poor prognosis in many cancer types, including lung adenocarcinoma (LUAD)." (PMID 34737838, 2021). "Our results provide new insights into the role of FH in tumors, suggesting that FH is related to the immune infiltration of a variety of tumors and is a potential prognostic biomarker, especially in lung adenocarcinoma (LUAD)." (PMID 34737838, 2021).
Lyme disease (2 papers, 2009 to 2024). Lyme disease (named after the towns in the USA where the disease was first identified) is a bacterial infection caused by Borrelia burgdorferi. "We show novel murine fH putative ligands expressed by Lyme disease Borrelia and B. coriaceae." (PMID 19604355, 2009). "For instance, although several different outer surface proteins of Borrelia burgdorferi, the causative agent of Lyme disease, have been identified as being able to bind host FH, it has been shown that FH is not essential for mammalian infection by this spirochete." (PMID 38698856, 2024). "We and others have reported that cattle and horses are not suitable hosts for Lyme disease related Borreliae, which strongly correlates with the inability of borrelial proteins to bind bovine and equine fH." (PMID 19604355, 2009).
meningococcal disease (2 papers, 2012 to 2017). "However, a targeted genotyping approach has revealed a polymorphism in a putative nuclear-factor (NF)-κB responsive element in CFH, which probably decreases expression of fH, to be associated with meningococcal disease." (PMID 22749446, 2012). "Reduced levels of fH, a disadvantage for cell surface protection and therefore risk for aHUS, may be protective for meningococcal disease as fH is ‘hijacked’ for complement protection by Neisseria meningitidis through binding a bacterial surface receptor, fHbp." (PMID 22749446, 2012). "FHR-3 is not clearly associated with fH deregulation, and its role remains unclear; it can interact with the meningococcus fH-binding protein and through competition with fH, influence the complement-mediated clearance of meningococcal strains and hence meningococcal disease severity." (PMID 28673452, 2017).
mesenchymal neoplasm (2 papers, 2025). "dFH-LM is a rare but clinically important subtype of smooth muscle mesenchymal neoplasm that arises after inactivation of the FH gene." (PMID 41374387, 2025).
neurofibromatosis type 1 (2 papers, 2022 to 2024). A clinically heterogeneous, neurocutaneous genetic disorder characterized by cafe-au-lait spots, iris Lisch nodules, axillary and inguinal freckling, and multiple neurofibromas. "Since then, at least 20 susceptibility genes have been detected to have germline mutations, such as NF1 (neurofibromatosis type 1), TMEM127 (transmembrane protein 127), FH (fumarate hydratase), VHL (Von Hippel-Lindau), and others." (PMID 35627249, 2022).
osteosarcoma (2 papers, 2020 to 2024). A usually aggressive malignant bone-forming mesenchymal neoplasm, predominantly affecting adolescents and young adults. "Given that TOMM40 and FH are upregulated in the osteosarcoma metastasis group, we further analyzed the pan-cancer characteristics of TOMM40 and FH." (PMID 38285218, 2024). "We finally found that TOMM40 and FH can significantly promote osteosarcoma metastasis, and the pro-metastatic ability of TOMM40 and FH was verified by in vitro experiments." (PMID 38285218, 2024). "Meanwhile, wound healing showed that si-TOMM40 and si-FH reduced the invasive ability of osteosarcoma cell lines." (PMID 38285218, 2024). "Western blot further demonstrated a higher expression of TOMM40, FH in the metastatic group of osteosarcoma patients." (PMID 38285218, 2024). "However, there are few studies on the mechanism of action of TOMM40 and FH in osteosarcoma." (PMID 38285218, 2024). "According to the Western blot results, the expression of TOMM40 and FH was higher in the metastatic tissues of osteosarcoma than in the non-metastatic group." (PMID 38285218, 2024). "qPCR results showed significant differences in the expression of TOMM40 and FH mRNA in the metastatic and non-metastatic groups of osteosarcomas." (PMID 38285218, 2024). "Through experimental validation analysis, TOMM40, FH RNA expression was shown to be significantly different in Osteosarcoma metastasis group and non-metastasis group tissues." (PMID 38285218, 2024).
thrombotic microangiopathy (2 papers, 2013 to 2025). The syndromes of microangiopathic hemolytic anemia, thrombocytopenia, and variable signs of organ impairment, due to platelet aggregation in the microcirculation. "Our data introduce the hypothesis that fH may contribute to clinical thrombotic microangiopathies through a complement-independent mechanism." (PMID 23991205, 2013). "This functional interaction between fH, VWF and ADAMTS-13 could contribute to the pathogenesis of thrombotic microangiopathy in both TTP and aHUS and provide a mechanistic basis for the frequently observed clinical overlap between TTP and HUS." (PMID 23991205, 2013). "The mechanism linking abnormal function of fH to thrombotic microangiopathy in aHUS is not clear." (PMID 23991205, 2013).
thyroid (2 papers, 2015 to 2022). "Other tumours less relevant to this case include tubulocystic RCC, acquired cystic disease associated RCC, Fumarate hydratase deficient RCC, papillary RCC, and thyroid-like follicular carcinoma of the kidney." (PMID 34514562, 2022).
uterine cancer (2 papers, 2015 to 2025). Primary or metastatic malignant neoplasm involving the uterine corpus and/or the cervix. "For example, germline mutation in fumarate hydratases (FH) is reported high in familial cancer syndromes, and in skin, renal and uterus cancers." (PMID 26437434, 2015). "The concordance rate was 75%, as the tumor genomic profiling in a case of uterine cancer did not identify the FH P/LPGV." (PMID 41465149, 2025).
xanthoma (2 papers, 2018 to 2025). A non-neoplastic disorder characterized by a localized collection of histiocytes containing lipid. "A previous study found that HeFH patients with pathogenic FH mutations exhibited xanthomas at 6.3% and corneal arcus at 4.2%." (PMID 41303093, 2025). "Notably, there were two patients with xanthoma did not exhibit any FH mutation, indicating the difference between clinical features and genetic testing." (PMID 30526649, 2018).
acute-on-chronic liver failure (1 paper, 2025). Acute-on-chronic liver failure (ACLF) is an extreme condition during the natural history of chronic HBV infection, with a relatively high short-term mortality. "In the context of liver pathophysiology, anti-FH autoantibodies serve as prognostic biomarkers for Acute-on-Chronic Liver Failure." (PMID 40034261, 2025).
Bradycardia (1 paper, 2023). A slower than normal heart rate (in adults, slower than 60 beats per minute). "Further, this study examined the salmon's fH response to hypoxia and the oxygen level at which bradycardia was initiated in free-swimming fish versus those post-surgery in a respirometer." (PMID 37622446, 2023).
breast tumors (1 paper, 2025). "Comparison of FH-deficient and high-FH breast tumors revealed a significant increase in activated mast cells, which are implicated in tumor proliferation and angiogenesis, with an additional increase detected in resting memory CD4+ T cells." (PMID 41008787, 2025).
cardiac tumor (1 paper, 2018). "Although we fail to provide solid evidence to support that germline FH (E404D) and ACOX2 (R409H) are a direct cause of tumorigenesis in the heart, our results suggested that these two variants have combined effects on metabolic dysfunction in the cardiac tumor." (PMID 30062063, 2018).
cerebral malaria (1 paper, 2017). A sequestration of Plasmodium falciparum in the brain, which can cause coma and/or seizures. "In this study, the role of FH and MQO in the pathogenicity of asexual-blood-stage Plasmodium parasites causing cerebral malaria was examined." (PMID 28606087, 2017). "However, the importance of FH and MQO for asexual-stage parasite viability and growth in cerebral malaria is unclear." (PMID 28606087, 2017).
chordoma (1 paper, 2024). Chordomas are rare malignant tumors arising from embryonic remnants of the notochord in axial skeleton. "A 31-year-old female patient with a clival conventional chordoma was found to have a mutation in the FH gene (c.1431_1433dupAAA/p.K477dup)." (PMID 38700789, 2024). "All patients except for the RAD51C and FH heterozygotes, were referred to the NIH without prior knowledge of their germline status and had been followed according to the chordoma screening protocol, as recommended in the published guidelines by the Chordoma Global Consensus Group in 2017." (PMID 38700789, 2024).
Cognitive impairment (1 paper, 2022). Abnormal cognition is characterized by deficits in thinking, reasoning, or remembering. "Higher serum levels of C1q, C3 and FH in the cognitive impairment only group indicate that activation of the classical pathway and inhibition of the alternative pathway underlie the neuronal damage within this group." (PMID 35370615, 2022). "In this study, we found that there were significant differences between patients with cognitive impairment only, T2DM, or T2DM with cognitive impairment in the levels of the complement proteins C1q, C3, C3b and the complement regulatory protein FH." (PMID 35370615, 2022). "We conducted a cross-sectional study to prospectively determine the specific complement activating pathway, which includes different complement proteins (C1q, C3, C3b, C4, FH), in the pathology of T2DM only, cognitive impairment only, and T2DM combined with cognitive impairment." (PMID 35370615, 2022).
COVID-19 (1 paper, 2021). A disease caused by infection with severe acute respiratory syndrome coronavirus 2. "Despite evidence of systemic complement activation and activation of coagulation in cancer patient cohorts with and without COVID-19 and elevated D-dimers, C1 INH and FH levels remained within published reference ranges (Quidel MicroVue C1-Inhibitor Plus EIA." (PMID 34491250, 2021).
cutaneous squamous cell carcinoma (1 paper, 2022). "Knockdown of FH expression in cutaneous squamous cell carcinoma suppressed the cell proliferation and migration through inhibited ERK1/2 and p38 signaling." (PMID 36338737, 2022).
dengue (1 paper, 2024). "FH polymorphisms and haplotypes that result in altered FH expression were found protective against severe dengue." (PMID 38410512, 2024).
diffuse astrocytoma (1 paper, 2018). A low-grade (WHO grade II) astrocytic neoplasm.
Dyskinesia (1 paper, 2022). A movement disorder which consists of effects including diminished voluntary movements and the presence of involuntary movements.
eosinophilia (1 paper, 2024). "In this case of FH-deficient pRCC, a heavily pre-treated patient who responded remarkably to late nivolumab rechallenge accompanied by eosinophilia illustrates the potential of immunotherapy in managing such aggressive malignancies." (PMID 39496729, 2024).
focal epilepsy (1 paper, 2020). A seizure caused by a localized disorder. "We also identified a fumarate hydratase (fumarase) deficiency case which showed severe weakness, generalized severe hypotonia, focal epilepsy and infantile spasms and developmental delay." (PMID 32999401, 2020).
head and neck cancer (1 paper, 2022). A primary or metastatic malignant neoplasm affecting the head and neck. "The missing piece is the requisite evidence to show an altered fumarate level or fumarate hydratase activity in head and neck cancer cells, namely, FaDu cells; however, evidence has revealed metabolic reprogramming and increased 2-hydroxyglutarate levels in head and neck squamous cell carcinoma." (PMID 35897987, 2022).
Insulin resistance (1 paper, 2022). Increased resistance towards insulin, that is, diminished effectiveness of insulin in reducing blood glucose levels. "There was an association between C1q, C3, C4, and FH and β-pancreas cell function, whereas only FH was associated with insulin resistance." (PMID 35370615, 2022). "In summary, we found associations between increased levels of complement proteins, particularly FH, and insulin resistance." (PMID 35370615, 2022). "In the present study, we reveal a significant relationship between the elevated complement proteins C1q, C3, C4, and FH and enhanced β-cell function (HOMA-β) and insulin resistance (HOMA-IR)." (PMID 35370615, 2022).
leukopenia (1 paper, 2017). "Consistent with this, we also found that monozygous twins with recessive FH mutations display leukopenia and neutropenia, thus suggesting a role for FH in the regulation of hematopoiesis." (PMID 28202494, 2017).
lung squamous cell carcinoma (1 paper, 2021). "Additionally, FH expression was associated with immune infiltration, including B cells, CD4+ T cells, CD8+ T cells, neutrophils, macrophages, and dendritic cells, especially in liver hepatocellular carcinoma (LIHC), LUAD, and lung squamous cell carcinoma (LUSC)." (PMID 34737838, 2021).
lupus nephritis (1 paper, 2020). Glomerulonephritis in the context of systemic lupus erythematosus. "Activation of the alternative pathway, seems essential too, given that more C3 than C4 deposits, that deficiencies of factors of the alternative pathway, like FB and FD, ameliorate lupus nephritis, and that deficiencies of its inhibitory factors, like FH, promote lupus nephritis in animal models." (PMID 33643288, 2020).
major depression disorder (1 paper, 2022). "In it, patients with a positive FH had a lower major depression disorder rate (25.4%) than patients with a negative FH (63.6%), which was consistent with our study results." (PMID 36389504, 2022).
malaria (1 paper, 2022). Malaria is a serious and sometimes fatal disease caused by a parasite that commonly infects a certain type of mosquito which feeds on humans. "The concentration of serum FH in severe malaria is higher than that in uncomplicated malaria, supporting its roles in immune evasion and host clinical manifestations." (PMID 35271623, 2022).
male infertility (1 paper, 2023). The inability of the male to effect fertilization of an ovum after a specified period of unprotected intercourse. "Among these were well-studied protein biomarkers for male infertility such as IDH3A, GAPDHS, FH, and DLAT." (PMID 36509450, 2023).
mantle cell lymphoma (1 paper, 2024). Mantle cell lymphoma is a rare form of malignant non-Hodgkin lymphoma affecting B lymphocytes in the lymph nodes in a region called the ``mantle zone''. "Analysis of the FH gene in specific tumors from mantle cell lymphoma (MCL) patients has shown a secondary mutation that deactivates the normal allele, followed by the loss of the wild-type allele." (PMID 39201746, 2024).
mental retardation (1 paper, 2023). "Examples of cause by absence (c-a) are Anion Exchanger 1 in Spherocytosis; Fumarate Hydratase in Fumarase Deficiency Disease (FHD, OMIM 606812); Securin in cancer; Methyl-CpG-Binding Protein 2 in mental retardation (MR, OMIM 300055); or PKM in cardiovascular disease." (PMID 36672169, 2023).
mucinous tumors (1 paper, 2012). "These include: FH, GMPS, PIK3CA, EIF4A2, ZNF384, and SS18L1 (amplifications in serous tumors); TET2, FGFR10P, NF1, ERBB2, and SH3GL1 (deletions in serous tumors) and ERBB2 (amplifications in mucinous tumors)." (PMID 23078675, 2012).
non-alcoholic fatty liver disease (1 paper, 2024). "Itaconate is known to modulate the immune and antioxidant responses, and miR-144, by preventing itaconate synthesis, increases FH activity, potentially contributing to non-alcoholic fatty liver disease." (PMID 38517358, 2024).
ovarian mucinous cystadenoma (1 paper, 2021). "Mutation of Ala274 to a valine in human fumarate hydratase (FH) was implicated in ovarian mucinous cystadenoma, and resulted in a 50% decreased activity of the enzyme." (PMID 34656184, 2021).
pituitary adenoma (1 paper, 2015). "Known pheo/PGL genes (SDHA-D, SDHAF2, RET, VHL, TMEM127, MAX, FH) and pituitary adenoma genes (MEN1, AIP, CDKN1B) were sequenced using next generation or Sanger sequencing." (PMID 25494863, 2015).
polycystic kidney disease (1 paper, 2025). A usually autosomal dominant and less frequently autosomal recessive genetic disorder characterized by the presence of numerous cysts in the kidneys leading to end-stage renal failure. "No pathogenic variant in a FH gene was detected and only one pathogenic variant in a MGH gene, in a patient with polycystic kidney disease which was evident even without genetic testing." (PMID 39910139, 2025).
polycythemia (1 paper, 2024). Abnormally high mass or concentration of red blood cells in the blood, either due to an increase in erythropoiesis or a decrease in plasma volume. "18F-DOPA is a radiotracer that accumulates specifically in some PPGLs due to increased uptake by amino acid transporters: 18F-DOPA PET/CT represents the functional imaging of choice in cluster 1B and cluster 2 PPGLs, as well as in FH mutated and polycythemia-related PPGLs." (PMID 38543140, 2024).
Primary Immunodeficiency (1 paper, 2026). "In both FH- and FH+ family members, symptoms suggestive of Primary Immunodeficiency (PID) were present in 32.1 to 61.5% (p = 0.29)." (PMID 41909677, 2026).
renal dysfunction (1 paper, 2021). "In support of this hypothesis, a recent study also found that a FH polymorphism significantly lowering plasma FH levels increased the risk for both renal dysfunction and cardiovascular events in a study of over 1100 human T2D patients." (PMID 34159399, 2021).
sarcoma (1 paper, 2015). A usually aggressive malignant neoplasm of the soft tissue or bone.
syndromic (1 paper, 2025). "In this study, we focused on syndromic disorders caused by seven tumor suppressor genes: FH, NF1, PTCH1, RB1, STK11, and TSC1/2." (PMID 40702147, 2025).
testicular germ cell tumor (1 paper, 2021). A germ cell tumor arising from the testis. "Moreover, FH expression showed a strong correlation with immune checkpoint markers in LUAD and testicular germ cell tumors (TGCT)." (PMID 34737838, 2021).
trachoma (1 paper, 2019). "Core gene coding for fumarate hydratase, class II (OG134) harbors nonsense mutation in 8 trachoma strains (serovars A-C) and frameshift in 22 LGV strains (L1-L3) and one urogenital strain (D-K)." (PMID 31510914, 2019).
type 1 diabetes (1 paper, 2020). "Here, we investigate fumarate hydratase activity in biofluids in combination with the molecular imaging probe, hyperpolarized [1,4-13C2]fumarate, to identify the early changes associated with hemodynamics and cell death in a streptozotocin rat model of type 1 diabetes." (PMID 32541797, 2020).
uterine tumors (1 paper, 2026). "Awareness of FH-deficient uterine tumors is essential, as their recognition depends on familiarity with their distinctive morphological patterns and the systematic use of both FH and 2SC immunohistochemical markers." (PMID 41438660, 2026).